MYCN (MYCN proto-oncogene, bHLH transcription factor)
Diseases named in the same sentence as MYCN in open-access papers (continued):
Sharing a sentence is not in itself a finding about the gene and the disease.
neuroblastoma (continued). "Moreover, a study reports that the sensitivity to apoptosis of MYCN-overexpressing neuroblastomas is increased through the DNA damage response." (PMID 34591871, 2021). "In neuroblastoma, MYCN was recently found to regulate the entire polyamine metabolic pathway." (PMID 33579942, 2021). "Tumor infiltration of adjacent organs and structures was associated with decreased survival (HR = 8.90, p = 0.007), MYCN amplification (OR = 9.91, p = 0.001), high MKI (OR = 6.20, p = 0.003), and increased risk of International Neuroblastoma Staging System stage 4 disease (OR = 8.96, p < 0.001)." (PMID 33314708, 2021). "Finally, silencing of either MYCN or TEAD4 largely modified the transcriptional signature of the cells toward a neuroblastoma stage 1 signature with decreased viability in vitro and in vivo." (PMID 34200747, 2021). "It has been shown that high levels of MYCN protein persist in MYCN-amplified neuroblastoma after transfecting high levels of let-7 miRNA and that MYCN, which is the most abundant target for let-7 miRNA, actually acts as a sponge for let-7 miRNAs in these cells." (PMID 35008302, 2021). "Interestingly, in the MYCN-amplified NGP neuroblastoma cell line, depletion of ARID1A using CRISPR-Cas9 promotes the transdifferentiation of NOR cells toward a MES state with increased invasion, migration, and resistance to cisplatin." (PMID 34200747, 2021). "However, in contrast with RB, neuroblastoma, another childhood malignancy, with MYCN amplification was shown to correlate with poor prognosis." (PMID 34680394, 2021). "However, the relationships of age and MYCN amplification in the predication of the clinical outcomes of neuroblastoma are unclear." (PMID 34116676, 2021). "Additionally, other important genetic markers for neuroblastoma are mutations in ALK, PTPN11, TERT, ATRX, and amplification of MYCN." (PMID 34885007, 2021). "Last, our study defined for the first time through a cross-species integrative transcriptomics approach putative master regulators for MYCN-driven neuroblastoma tumor development and revealed FOXM1 and the DREAM complex members MYBL2 and E2F8 as top-scoring candidates." (PMID 34638267, 2021). "Importantly, induction of differentiation in neuroblastoma cells requires early MYCN expression, followed by downregulation." (PMID 33659885, 2021). "Thus, our studies reveal that KDM6B regulates the oncogenic CDK4/6-pRB-E2F pathway in MYCN-amplified neuroblastoma, revealing a mechanism of regulation of the E2F transcriptome by an epigenetic modulator." (PMID 34893606, 2021). "The survival rates were not significantly changed in patients with high or low expression of MCM2 or MCM10 with MYCN-amplified neuroblastoma, suggesting that MYCN amplification is more dominant than MCM expression in determining poor prognosis in this patient subgroup." (PMID 35056094, 2021). "Vitally, even mutant RAS cloned from tumor tissue requires concurrent MYC overexpression for transformation to proceed, highlighting the importance of cooperation between MYCN amplification and oncogenic RAS mutations or activation of RAS-related pathways in neuroblastomas." (PMID 34069817, 2021). "Conversely, in primary neuroblastomas TrkB-FL expression has been found to be associated with MYCN gene amplification, an unfavorable prognostic marker, and its activation by BDNF has been shown to promote neuroblastoma cell survival, resistance to chemotherapy, anoikis and metastasis." (PMID 34360553, 2021). "Next, we tried to determine the associations of ALCAM, CACNA2D3, DST, EPB41L4A and KIF1B in MYCN non-amplified neuroblastoma patients." (PMID 34116676, 2021). "MYCN overexpression in neural crest progenitor cells leads to neuroblastoma formation." (PMID 34577571, 2021). "However, LIN28B is dispensable in MYCN-amplified neuroblastoma cell lines, despite de-repression of let-7." (PMID 34771690, 2021).
neuroblastoma (continued). "Interestingly, in human neuroblastoma cells Sp1 has been reported to form a repression complex with MYCN and MIZ1, and that Sp1 cell depletion has been found to induce the expression of p75NTR and TrkA." (PMID 34360553, 2021). "Hence, therapeutic reduction of MycN expression is a noteworthy approach to improve treatment of neuroblastoma 40 as supported by studies in mouse models of MYCN-driven neuroblastoma." (PMID 33390782, 2021). "In order to gain further insight into the possible early role of Ascl1 and Meis2 in MYCN-driven tumor formation compared to the other core regulatory circuit members, we compared their time-resolved expression during murine TH-MYCN-driven neuroblastoma tumor development." (PMID 34638267, 2021). "ALYREF protein expression levels were high in MYCN-amplified and MYCN overexpressing human neuroblastoma cells (lanes 1–7) across a panel of neuroblastoma cell lines, with significantly higher expression levels when compared to human fibroblasts (lanes 12 and 13; WI-38 and MRC5)." (PMID 33767157, 2021). "Furthermore, their expression levels were correlated with MYCN in two cohorts of WT patients and a neuroblastoma data set." (PMID 34689785, 2021). "To evaluate whether combination therapy increased MYCN degradation through ubiquitination and the proteasomal pathway, we treated neuroblastoma cells with combination therapy for 24 h and then added the proteasome inhibitor MG-132 (30 μM) for 4 h." (PMID 33658627, 2021). "In addition to MYCN amplifications, other chromosomal abnormalities commonly occur in neuroblastoma." (PMID 34458583, 2021). "Gain at chromosome 17q21 in neuroblastoma is associated with a poor prognosis, independent of MYCN amplification status." (PMID 33796454, 2021). "Furthermore, the authors demonstrated that MYCN overexpressing neuroblastoma cells are addicted to Alt-NHEJ repair for survival." (PMID 33808562, 2021). "However, even in some MYCN-amplified BETi-sensitive neuroblastoma lines, a portion of cells survive the treatment, as documented by the Emax values (range: 55–100%), with some MYCN-amplified lines described as BETi-resistant." (PMID 33668642, 2021). "So, next, we determined the relationships of age and MYCN amplification in neuroblastoma." (PMID 34116676, 2021). "MYCN is located on chromosome 2p24.3 and is amplified in 20–25% of neuroblastoma cases." (PMID 34885007, 2021). "Knockdown of USP3 had marked effects on the cancer phenotype in MYCN-amplified neuroblastoma cells." (PMID 33767157, 2021). "We proceeded to evaluate the impact of MYCN levels on fatty acid metabolism in neuroblastoma cells." (PMID 33659885, 2021). "MYCN amplification is an important prognostic factor in neuroblastoma." (PMID 34116676, 2021). "Amplification of the MYCN oncogene, which occurs in approximately 20% of cases, is one of the clearest markers for identifying high-risk neuroblastoma patients, regardless of disease stage." (PMID 33968920, 2021). "Notably, we detected the presence of hexokinase II and PKM2 in EVs circulating in the bloodstream of neuroblastoma patients and more frequently in those bearing MYCN-amplified tumours." (PMID 34847775, 2021). "In addition, CDX2 was predicted to regulate MYCN, a transcription factor commonly amplified in aggressive neuroblastoma." (PMID 32940375, 2021). "PI3Kα inhibitor PIK-75 (78.9% cytotoxicity) stimulates anti-neuroblastoma activity by destabilizing MYCN and sensitizing tumor cells to anthracyclines, and indeed increased cytotoxicity with PIK-75 was associated with PPM1D and GNA13 gain, and DNMT3A, CBL, EED and ASXL2 loss." (PMID 34722256, 2021).
neuroblastoma (continued). "Based on the International Neuroblastoma Risk Group (INRG) classification system—which takes into account age at diagnosis, histopathological features, MYCN status, DNA index and segmental chromosomal aberrations (SCA)—patients can be placed into a low-, intermediate- or high-risk group." (PMID 34204830, 2021). "We therefore hypothesized that MYCN could promote neuroblastoma growth by regulating the secretion or content of extracellular vesicles (EVs) which would modify the metabolic activity of recipient cells." (PMID 34847775, 2021). "The hypothesis that MYC expression could induce non-cell autonomous effects is also supported by evidence of heterogeneous (focal) amplification of MYCN in neuroblastoma tumours." (PMID 34847775, 2021). "The recent report of successful combined use of AURKA CD inhibitors and ATR inhibitors in MYCN amplified neuroblastoma strengthens the potential value of using compounds disrupting both AURKA activity and the interaction with N-Myc for the treatment of this highly aggressive tumor type." (PMID 34884931, 2021). "Integration of multi-omic MYCN datasets revealed strong support for the hypothesis that targeting epigenetic regulatory mechanisms in MYCN amplified neuroblastoma will likely provide beneficial future therapeutic strategies." (PMID 33968920, 2021). "MYCNOS promotes the invasion and metastasis of neuroblastoma and rhabdomyosarcoma by regulating MYCN protein and may participate in the development of WT." (PMID 33718161, 2021). "Therefore, deeper understanding of MYCN dependent epigenetic vulnerabilities provides a novel route for targeted therapies in neuroblastoma." (PMID 33968920, 2021). "We propose that a tumor‐specific, MYCN‐targeted siRNA (siMYCN) treatment for disseminated neuroblastoma may be achieved by systemic administration of the siRNA encapsulated in a suitable nanoparticle formulation." (PMID 35712226, 2021). "Using published gene expression datasets, previously, we had identified six MYCN target genes which could be used to predict the clinical outcomes of neuroblastoma." (PMID 34116676, 2021). "Reportedly, ATM silencing promotes neuroblastoma progression independently of MYCN amplification." (PMID 34796286, 2021). "CRABP-II increases expression of the oncogene MycN that inhibits apoptosis of neuroblastoma cells." (PMID 32326273, 2020). "In a model of MYCN-amplified neuroblastoma cells, experimental overexpression of miR-101 and let-7e induced a decrease in MYCN protein levels and inhibited cell growth via the direct regulation of MYCN." (PMID 33937011, 2020). "In addition, targeting BRD4 by BET inhibitor displaces BRD4 from the MYCN promoter region and downregulates MYCN expression in neuroblastoma cells, establishing BRD4 as a transcriptional regulator of MYCN." (PMID 33324552, 2020). "In these cases, MYCN amplification is likely an early driver of neuroblastoma formation." (PMID 33199677, 2020). "Furthermore, overexpression of MYCN in primary neural crest cells isolated from an embryonic neural tube explant developed tumors that were highly similar to MYCN amplified neuroblastoma when the cells were inoculated in mice." (PMID 33585251, 2020). "Our results suggest that upon glutamine deprivation, MYCN expression could modulate a specific group of DNA repair genes having a similar function in neuroblastoma." (PMID 32483461, 2020). "Finally, we examined if CAMKV protein expression is selectively expressed in MYCN amplified neuroblastoma cell lines." (PMID 32211329, 2020). "The 5′UTR of MYCN contains important regulatory elements for promoter activity in neuroblastoma." (PMID 32586373, 2020). "Here the authors analyse the MYCN amplicon structure and its epigenetic regulation by integrating short- and longread genomic and epigenomic data and find two classes of MYCN amplicons in neuroblastomas, one driven by local enhancers and the other by hijacking of distal regulatory elements." (PMID 33199677, 2020).
neuroblastoma (continued). "Our data revealed that ALDH1A1 and ALDH1A3 mRNA expression positively correlates with c-MYC gene expression in the neuroblastoma patient samples, and siRNA-mediated c-MYC knockdown inhibited expression of ALDH1A2 and ALDH1A3 genes in the MYCN-amplified neuroblastoma cells." (PMID 32483461, 2020). "Similarly, neuroblastomas driven by MYCN amplification, which promotes the formation of aberrant SEs, are selectively sensitive to CDK7 inhibition." (PMID 32385714, 2020). "Also, in the case of MYCN amplified tumours, transcriptional up-regulation of TERT is only one of many oncogenic programmes up-regulated in MYCN amplified neuroblastoma cells." (PMID 32375866, 2020). "MYCN amplification status is routinely tested for in all newly diagnosed neuroblastoma patients, and we sought to discover therapeutic targets that could utilize MYCN amplification as a biomarker for efficacy." (PMID 32211329, 2020). "Although a large amount of molecular data were obtained from neuroblastoma, the situation appears complex as this tumor displays heterogeneous clinical behavior depending on multiple factors including tumor stage, patient age, and MYCN oncogene amplification." (PMID 32664294, 2020). "Moreover, MYCN amplification was also an independent prognostic marker in patients with neuroblastoma in GSE85047 dataset." (PMID 32593299, 2020). "We next searched the neuroblastoma immunopeptidomics dataset we created for peptides derived from the MYCN oncogene, a major cancer driver in neuroblastoma, finding only a single peptide (KATEYVHSL) presented on the relatively rare HLA-C*16:01 allele representing <5% of the population." (PMID 32256484, 2020). "In neuroblastoma, MYCN interacted with OCT4 to promote the function of CSCs." (PMID 32857725, 2020). "PARP inhibition alone or in combination with classical chemotherapeutics is therefore a potential therapeutic strategy for neuroblastoma and may be more effective in MYCN expressing tumours." (PMID 32577161, 2020). "Collectively, these results highlight a complex interplay between c-MYC and MYCN that could regulate radioresistance properties upon glutamine deprivation in neuroblastoma cells." (PMID 32483461, 2020). "Here, we nominate CAMKV as an immunotherapeutic target for MYCN amplified neuroblastoma, and suggest pursuing the identification of specific human scFv binders to this protein for the creation of antibody-drug conjugate therapeutics that should not cross the blood-brain barrier." (PMID 32211329, 2020). "PI3K inhibitors are also reported to kill neuroblastoma cells by inducing degradation of MYCN." (PMID 32722460, 2020). "MYCN is often amplified in aggressive neuroblastomas and highly correlated with advanced disease." (PMID 32686724, 2020). "In addition, the targeted delivery of miR-186 to MYCN-amplified neuroblastoma cells or natural killer cells resulted in significant tumor growth inhibition." (PMID 33937011, 2020). "Inhibitors of PLK1, such as BI6727 and BI2356, preferentially trigger apoptosis of MYCN-amplified neuroblastoma and small cell lung cancer, and this therapeutic efficacy is synergistically enhanced by combined use with antagonists of anti-apoptotic B cell lymphoma 2 (BCL2)." (PMID 33614505, 2020). "A related immunosuppressant, mycophenolic acid, a potent inosine monophosphate dehydrogenase (IMPDH) inhibitor, was shown to induce senescence in imatinib-resistant chronic myelogenous leukemia cells, while hydroxyurea induced senescence in MYCN-amplified neuroblastoma cells." (PMID 32235364, 2020).
neuroblastoma (continued). "Thus, intervention with glutamine metabolism in neuroblastoma cells uncovered cell-type specific adaptations and metabolic dependencies modulated by MYCN expression and glutamine levels." (PMID 32346009, 2020). "In particular, the reference scenario contains a subset of 80 high-risk neuroblastoma samples forming two groups: the MYCN amplified (n1 = 40) and MYCN non-amplified (n2 = 40)." (PMID 32306892, 2020). "In 2015 it was reported that aggressive neuroblastoma can be divided into 3 almost mutually exclusive subgroups with either MYCN amplification, rearrangements upstream to the telomerase reverse transcriptase (TERT) gene or alternative lengthening of telomeres (ALT)." (PMID 32375866, 2020). "Approximately 20% of neuroblastomas show MYCN gene amplification." (PMID 33194665, 2020). "In summary, our studies define the MK2/OCT4/c-MYC axis as a novel mechanism of MYC transcriptional activation in neuroblastoma that mediates resistance to 13-cisRA by rescuing 13-cisRA induced MYCN downregulation and is commonly found in progressive disease neuroblastomas." (PMID 32409685, 2020). "Using CEN‐tools, we isolated such genes and revealed a subnetwork consisting of a number of transcription factors (TFs) that are known to control tissue differentiation into a specific lineage such as SOX10 in skin, PAX8 in ovary, kidney and endometrium (, and MYCN in neuroblastoma." (PMID 33073517, 2020). "Although MYCN gene amplification is detected in approximately 50% of high-risk neuroblastoma cases and an oncogenic driver for neuroblastoma, there exists no current evidence describing when and how the amplification of the MYCN gene is initiated." (PMID 33585251, 2020). "Interestingly, CD68-positive TAMs co-expressing IL-6 was identified in the metastatic bone marrow samples of non-MYCN-amplified neuroblastoma." (PMID 32983125, 2020). "STAT3 directly mediates the initiation of MYCN transcription in neuroblastoma cells." (PMID 33937011, 2020). "In summary, MYCN expression leads to increased replication stress in neuroblastoma cells." (PMID 32577161, 2020). "It is important as an additional potential mechanism by which MYCN may induce the SCD of neuroblastoma stem cells." (PMID 33194665, 2020). "However, the globe MYCN amplification regulated genes and their predictive relevance in neuroblastoma are unclear." (PMID 32593299, 2020). "On the other hand, a similar role of the PRMT1-ATF5 axis may apply to neuroblastomas with low MYCN levels." (PMID 32415090, 2020). "CHK1 transcription is markedly elevated in patients with MYCN-amplified neuroblastomas." (PMID 32547946, 2020). "MYCN oncogene amplification is a marker of poor prognosis in patients with neuroblastoma disease." (PMID 32117438, 2020). "Additionally, a well characterized differentiation block of NCCs, resulting in neuroblastoma, depends on MYCN amplification and over-expression, with MYCN transcriptionally repressing genes required for sympathetic nervous system differentiation." (PMID 32210188, 2020). "Furthermore, the transcriptional activity of MYCN is important for inducing SCD in human neuroblastoma cells." (PMID 33194665, 2020). "However in neuroblastoma, in pre-clinical studies, co-targeting of retinoid and TGFβ signaling pathways through combination of retionoic acid and Kartogenin (TGFβ signaling activating molecule) has decreased the viability of MYCN amplified neuroblastoma cells." (PMID 32722460, 2020). "Consistent with the previous report that MYCN amplification was associated with poor outcome, neuroblastoma patients with MYCN amplification had worse prognosis than patients without MYCN amplification in TARGET dataset." (PMID 32593299, 2020). "High-risk, MYCN single copy neuroblastomas often express MYC as the oncogenic driver while MYCN is not expressed in these cells." (PMID 33585251, 2020). "Amplification of the MYCN locus was first observed in human neuroblastoma." (PMID 33937011, 2020).